DGAT2 (diacylglycerol O-acyltransferase 2)
Diseases named in the same sentence as DGAT2 in open-access papers (continued):
Sharing a sentence is not in itself a finding about the gene and the disease.
Charcot-Marie-Tooth disease (2 papers, 2021 to 2023). An inherited degenerative disorder involving the peripheral nerves. "DGAT2 mutations are also associated with physiological alterations like Charcot-Marie-Tooth disease in humans, compromising muscle structure and function." (PMID 34439946, 2021). "In addition, DGAT2 mutations are associated with the phenotype of impaired muscle structure and function (e.g., Charcot-Marie-Tooth disease) in humans and cellular transformation properties in several types of human cancer." (PMID 37644753, 2023). "Additionally, we find that DGAT2 mutations in cancer cells are distinguishable from a conserved mutation that is linked to Axonal Charcot-Marie-Tooth disease, an inherited condition leading to muscle degeneration." (PMID 34439946, 2021).
lipid metabolic disorder (2 papers, 2019 to 2023). "To explore the underlying mechanism behind TDQ's intervention in glucose and lipid metabolism disorder, we analyzed the gene and protein changes of PPARγ and DGAT2 expression in the livers." (PMID 31019978, 2019). "TDQ are, therefore, a potential Chinese medicinal formula that relieves IR and lipid metabolism disorder might be through promotion of PPARγ and decrease of DGAT2 expression." (PMID 31019978, 2019).
prostate carcinoma (2 papers, 2020 to 2025). A carcinoma that arises from epithelial cells of the prostate gland. "Also, DGAT2 has been reported to be associated with the regulation of the development of prostate cancer." (PMID 32285560, 2020).
psoriasis (2 papers, 2019 to 2025). An autoimmune condition characterized by red, well-delineated plaques with silvery scales that are usually on the extensor surfaces and scalp. "Our study highlights the critical role of DGAT2 and lipid metabolism in the pathogenesis of psoriasis." (PMID 40694426, 2025). "Our results show that DGAT2 expression was reduced and glyceride metabolism was disrupted in psoriatic lesions in both patients with psoriasis and Spry1ΔEpi mice." (PMID 40694426, 2025). "The dysregulation of DGAT2 and lipid metabolism enhances TLR3-mediated inflammation in keratinocytes and promotes CD8+ T cell activation, driving psoriasis development in keratinocyte-specific SPRY1-deficient mice." (PMID 40694426, 2025). "We observed decreased DGAT2 expression and abnormal glyceride metabolism in the epidermis of both patients with psoriasis and Spry1ΔEpi mice." (PMID 40694426, 2025). "Using both psoriasis patient samples and Spry1ΔEpi mice, we investigated the role of diacylglycerol acyltransferase 2 (DGAT2) in psoriasis." (PMID 40694426, 2025). "We observed increased DGAT2 levels in the supernatant of keratinocytes derived from patients with psoriasis compared with healthy controls, despite reduced intracellular DGAT2 expression." (PMID 40694426, 2025). "We observed decreased DGAT2 expression and abnormal glyceride metabolism in the psoriatic lesions of Spry1ΔEpi mice and patients with psoriasis." (PMID 40694426, 2025). "We further investigate the role of DGAT2 and lipid metabolism abnormalities in the pathogenesis of psoriasis." (PMID 40694426, 2025). "Our results highlight that keratinocytes from patients with psoriasis secrete increased levels of DGAT2." (PMID 40694426, 2025). "In this study, we investigate the role of DGAT2 and lipid metabolism in the skin lesions of both a psoriasis-like mouse model (Spry1ΔEpi mice) and patients with psoriasis." (PMID 40694426, 2025). "The observed positive correlation between SPRY1 and DGAT2 mRNA levels in psoriasis datasets may reflect a shared upstream regulatory mechanism, which needs further investigation." (PMID 40694426, 2025). "A study has reported that Dgat2 gene was decreased in human psoriatic skin, while its role in psoriasis is largely unknown." (PMID 40694426, 2025). "Given the abnormalities of glycerides in psoriasis lesions and the key role of DGAT2 in glyceride metabolism, we examined the expression of DGAT2 in psoriasis using datasets from the National Center for Biotechnology Information (NCBI) Gene Expression Omnibus (GEO), such as GSE30999 and GSE13355." (PMID 40694426, 2025). "Humans with DGAT2 deficiency appear not to have such marked skin abnormalities, although DGAT2 function has been linked to psoriasis." (PMID 30936184, 2019). "Furthermore, in an in vitro psoriasis model where normal keratinocytes were stimulated with the M5 cytokine cocktail (TNF-α, IL-17A, IL-22, IL-1α, and oncostatin M), DGAT2 expression was similarly reduced." (PMID 40694426, 2025).
triple-negative breast carcinoma (2 papers, 2025). An invasive breast carcinoma which is negative for expression of estrogen receptor (ER), progesterone receptor (PR), and human epidermal growth factor receptor 2 (HER2). "Moreover, IRE1α-dependent RIDD activity contributes to lipid metabolic reprogramming in triple-negative breast cancer (TNBC) by directly cleaving DGAT2 (diacylglycerol O-acyltransferase 2) mRNA, which encodes an enzyme critical for triacylglycerides biosynthesis and lipid droplet formation." (PMID 41228282, 2025).
viral infection (2 papers, 2024). "To rule out the potential off-target effects of short hairpin RNAs (shRNAs) on virus infection, we generated DGAT2RES cells by introducing human DGAT2-FLAG fusion gene with synonymous mutation in DGAT2-shRNA targeting sequence into DGAT2KD cells and tested the changes in viral replication levels." (PMID 39449854, 2024). "On the other hand, overexpression of DGAT2 depleted specific phospholipids, particularly oleyl fatty acyl chain-containing phosphatidylcholines, which, in contrast, are increased in HCV-infected cells and likely essential for viral infection." (PMID 39241103, 2024).
ZIKV infection (2 papers, 2024). "Further evidence needs to be provided to elucidate the mechanism of LD accumulation and expansion affected by DGAT2 upon ZIKV infection." (PMID 39449854, 2024). "In summary, we unveiled a novel mechanism of the lipid metabolism-related factor DGAT2 promoting ZIKV replication: Upon ZIKV infection, DGAT2 is cleaved by ZIKV protease NS2B3 to enhance its stability, providing more stable support for viral replication." (PMID 39449854, 2024). "To further test whether the enzyme activity of DGAT2 is required for LD formation, we introduced DGAT2-C3A-FLAG (with 3 key enzyme active sites mutated: C87A/C96A/C312A) into DGAT2KD cells and detected changes in LDs upon ZIKV infection." (PMID 39449854, 2024). "Considering that both ZIKV RNA and protein levels were reduced by DGAT2 knockdown, we hypothesized that DGAT2 acts on the early step of ZIKV infection." (PMID 39449854, 2024). "Importantly, DGAT2 was also cleaved in the context of ZIKV infection." (PMID 39449854, 2024). "In addition, inhibition of DGAT2 or combined treatment with both DGAT inhibitors did not reduce ZIKV infection, but marginally increased intracellular viral protein level, despite near-complete loss of LDs, which demonstrates complete inhibition of DGAT activity." (PMID 39237833, 2024). "The numbers and areas of LDs significantly decreased in DGAT2 KD cells, both with and without ZIKV infection, compared to control and DGAT1KD cells, indicating that ZIKV-induced LD formation is hindered upon DGAT2 disruption." (PMID 39449854, 2024).
alcoholic fatty liver disease (1 paper, 2019). Lipid infiltration of the hepatic parenchymal cells that is due to alcohol abuse. "DGAT2 is a rate-limiting enzyme that esterifies diacylglycerol in the final step of the hepatic TAG biosynthetic pathway, and contributed to chronic alcohol-induced alcoholic fatty liver disease." (PMID 31379584, 2019).
Arrhythmia (1 paper, 2024). Any cardiac rhythm other than the normal sinus rhythm. "While heart‐specific constitutive suppression of Dgat2 led to a higher arrhythmia index (AI), overexpression of human Dgat2 (hDgat2) resulted in reduced AI." (PMID 38616316, 2024).
atopic dermatitis (1 paper, 2025). "In the skin, DGAT2 is essential for preserving barrier integrity, as its expression inversely correlates with transepidermal water loss, a phenomenon notably observed in conditions such as atopic dermatitis." (PMID 40694426, 2025). "Reduced DGAT2 expression could also contribute to atopic dermatitis, a chronic inflammatory skin disease." (PMID 40694426, 2025).
Cirrhosis (1 paper, 2025). A chronic disorder of the liver in which liver tissue becomes scarred and is partially replaced by regenerative nodules and fibrotic tissue resulting in loss of liver function. "Among all, the top 5 hub genes identified for NAFLD vs. control were CXCL9, NOS2, SERPINE1, FABP4, and LPL, whereas AKR1D1, UGT2B17, CYP26B1, LIPC, and DGAT2 were identified as the top 5 hub genes for the NAFLD vs. cirrhosis group." (PMID 40365443, 2025). "Additionally, the top 5 biological functional hub genes in NAFLD vs. control (CXCL9, NOS2, SERPINE1, FABP4, and LPL) and NAFLD vs. cirrhosis (AKR1D1, UGT2B17, CYP26B1, LIPC, and DGAT2) groups were identified through PPI analysis among lipid, immune, and metabolism dysregulated genes." (PMID 40365443, 2025).
E. coli infection (1 paper, 2018). "In Mkp-1+/+ mice, E. coli infection downregulated the expression of Fasn and Scd1, but modestly increased the mRNA expression of Dgat2, an enzyme responsible for synthesis of triglyceride from fatty acid and glycerol." (PMID 30563203, 2018). "Second, the expression of Dgat2, the liver enzyme responsible for triglyceride synthesis from fatty acids and glyceride, was increased in Mkp-1+/+ mice after E. coli infection." (PMID 30563203, 2018). "Interestingly, in Mkp-1+/+ mice E. coli infection resulted in downregulation of genes that facilitate fatty acid synthesis but upregulation of Cd36 and Dgat2, whose protein products mediate fatty acid uptake and triglyceride synthesis, respectively." (PMID 30563203, 2018). "Dgat2 protein levels were significantly increased in Mkp-1+/+ mice following E. coli infection, but did not significantly change in Mkp-1−/− mice." (PMID 30563203, 2018).
endometrial tumor (1 paper, 2025). "Our laboratory analyses further confirmed the upregulation of both DGAT1 and DGAT2 in endometrial tumor tissues (unpublished data), supporting their role in lipid accumulation and reinforcing their inclusion in the diagnostic model." (PMID 40804485, 2025).
Glucose intolerance (1 paper, 2014). Glucose intolerance (GI) can be defined as dysglycemia that comprises both prediabetes and diabetes. "Reduction of diacylglycerol bydown-regulation of Dgat2 can improve glucose intolerance and restore hepatic insulinsignaling in mice." (PMID 25481429, 2014).
ischemia (1 paper, 2025). A hypoperfusion of the BLOOD through an organ or tissue caused by a PATHOLOGIC CONSTRICTION or obstruction of its BLOOD VESSELS, or an absence of BLOOD CIRCULATION. "Therefore, we hypothesized that modulating the expression or activity of Dgat2 may affect the sensitivity of cardiomyocytes to ischemia/reperfusion injury, which in turn alters the severity and recovery process of myocardial injury." (PMID 40510478, 2025).
keloid (1 paper, 2022). An irregularly shaped, elevated mark on the skin caused by deposits of excessive amounts of collagen during wound healing. "PPARGC1A, PPARG, PLIN1, LPL, ABHD5, lncRNA PART1, lncRNA ENTPD3-AS1 in trunk keloid and DGAT2 in ear keloid showed decreased trend under paired comparation." (PMID 35677827, 2022).
lipodystrophy (1 paper, 2019). A congenital or acquired disorder characterized by abnormal loss or redistribution of the adipose tissue in the body. "Based on the dramatic reduction of TG levels in animals lacking DGAT2 globally, we expected that ADGAT2 KO mice would have markedly reduced TG levels in adipose tissue, possibly even resulting in lipodystrophy." (PMID 30936184, 2019).
lung carcinoma (1 paper, 2022). "In agreement with this speculation, the pharmacological depletion of LDs by DGAT1 and DGAT2 inhibitor treatment significantly slows down cell growth and proliferation of lung cancer cells, especially those with higher LD contents, such as A549 and H460." (PMID 36293388, 2022).
lymphedema (1 paper, 2021). Excess fluid collection in tissues, causing swelling. "We also analysed the degree of differentiation at the mRNA expression levels of typical adipogenic markers (PPARγ, perilipin, FAS, DGAT2, ATGL) -but we could not find major differences between cells derived from lymphedema patients and control subjects." (PMID 33854130, 2021).
morbid obesity (1 paper, 2025). An excess of body weight, normally defined as an individual with a body mass index greater than 35 or a body weight greater than one hundred percent of ideal body weight. "In addition, we observed an upregulation of 10–30-fold for SCD, LIPIN1, and DGAT2 genes in low B12 primary Sc adipocytes derived from subjects with overweight and an increase of 20-fold for DGAT2 from subjects with morbid obesity (i–vi, p < 0.05)." (PMID 40264186, 2025).
mycobacterial infection (1 paper, 2025). "Additionally, the genes Mgll, Dgat2, Slc27a6, and Stard10 have been implicated in lipid metabolism, indicating that lipid metabolism may be disrupted in Gpr84−/− BMDMs during mycobacterial infection." (PMID 39858878, 2025).
myocardial ischemia (1 paper, 2025). A disorder of cardiac function caused by insufficient blood flow to the muscle tissue of the heart. "In this study, Dgat2, a critical gene for the interaction between mitochondrial metabolism and myocardial ischemia/reperfusion was discovered for the first time through bioinformatics analysis." (PMID 40510478, 2025). "This suggests that Dgat2 has a role in modulating the immune microenvironment during myocardial ischemia-reperfusion." (PMID 40510478, 2025). "In conclusion, we discovered Dgat2, a new potential mitochondria-related gene target in myocardial ischemia/reperfusion by comprehensive bioinformatics analysis and molecular experiments." (PMID 40510478, 2025). "It has also been found that the expression level of Dgat2 in cardiac tissue changes during myocardial ischemia/reperfusion injury." (PMID 40510478, 2025). "We found that Dgat2 could be exploited as a novel mitochondria-related gene target and biomarker in myocardial ischemia-reperfusion injury, which is of great clinical significance." (PMID 40510478, 2025). "Our investigation found a link between Dgat2 expression and the expression of specific immune cells, including alterations in neutrophils monocytes and T lymphocyte subsets, which were also key factors in the pathogenesis of myocardial ischemia/reperfusion." (PMID 40510478, 2025). "Therefore, we speculate that PPARG may be an essential target for regulating Dgat2 expression, and this potential regulatory pathway may provide a novel therapeutic strategy for myocardial ischemia-reperfusion injury, which is worthy of further investigation." (PMID 40510478, 2025). "However, investigations have only found that Dgat2 may have some heart-protective properties, and its significance in myocardial ischemia/reperfusion has not been published." (PMID 40510478, 2025).
neuroblastoma (1 paper, 2022). Neuroblastoma (NB) is the most common solid, extracranial childhood tumor. "NEST expression increased the mRNA levels of diacylglycerol acyltransferase 1 (DGAT1), but not DGAT2, the key enzymes of TG biosynthesis in neuroblastoma cells incubated with or without OA." (PMID 35888761, 2022).
neuropathy (1 paper, 2024). A disorder affecting the nervous system that manifests with pain, tingling, numbness, and/or muscle weakness. "DG also serve as a precursor for the synthesis of triglycerides by the enzyme diacylglycerol O-acyltransferase 2, which is increased in the sural nerves of diabetic patients with neuropathy and the sciatic nerves of type 2 DM mice with neuropathic pain." (PMID 38980579, 2024).
overnutrition (1 paper, 2024). An imbalanced nutritional status resulting from excessive intake of nutrients. "Because both DGAT1 and DGAT2 act on liver lipid droplet formation due to overnutrition, inhibition of DGAT1 alone does not usually improve lipid droplets." (PMID 38807157, 2024).
sarcoma (1 paper, 2025). A usually aggressive malignant neoplasm of the soft tissue or bone. "Validation using the public Gene Expression Profiling Interactive Analysis 2 sarcoma dataset confirmed consistent PLIN3 upregulation, and down-regulation of DGAT2 and CIDEC in tumor samples, mirroring our GbPDTO findings." (PMID 41376821, 2025).
Serratia Infections (1 paper, 2021). Infections with bacteria of the genus SERRATIA. "We showed that Serratia infection facilitated the accumulation of fatty acids by up-regulating the expression of FASN1 and DGAT2 in the lipogenesis pathway." (PMID 34073039, 2021). "Since Serratia infection increased lipogenesis by up-regulating FASN1 and DGAT2, we then quantified the lipid contents in the aphid fat body, and showed that Serratia-infected aphids had more triacylglycerols and larger lipid droplets than Serratia-free aphids." (PMID 34073039, 2021).